INS (insulin)
Diseases named in the same sentence as INS in open-access papers (continued):
Sharing a sentence is not in itself a finding about the gene and the disease.
Hypoglycemia (continued). "Therefore, multiple insulin infusion protocols (IIPs) were created, all meant to balance efficacy with safety (avoid hypoglycemia), and attainability (nursing workload)." (PMID 27878572, 2016). "Our results showed that blood insulin and glucose levels were elevated in rats with crush syndrome, which were reduced by Ani treatment with no risk of hypoglycemia." (PMID 27065867, 2016). "In addition, the effect of blood glucose, rate of hypoglycemia, and weight gain differ among insulin regimens." (PMID 27316668, 2016). "Briefly, the first formula proposed in 1922, using a very crude insulin preparation, was weight based and was calculated conservatively in order to avoid hypoglycemia and to preserve the limited amount of insulin available (body weight × insulin sensitivity in dogs [U/kg], divided by 2)." (PMID 27457238, 2016). "HbA1c change was comparable in fixed versus flexible regimens and hypoglycemia events occurred equally between both groups, showing that glargine 300U provides flexibility to occasionally adapt the timing of insulin injections to individuals’ daily changing lifestyle patterns." (PMID 26740822, 2016). "In absence of counterregulatory defect at the hormonal level, the delayed recovery from insulin-induced hypoglycemia could be due to an inability to mobilize glucose from endogenous stores." (PMID 27148080, 2016). "Second, hypoglycemia is a common side effect observed in insulin users." (PMID 26932742, 2016). "In fact, 33% of the study population originated in countries where breakfast was not the main meal of the day (Spain, India, Republic of Korea, Turkey), thus the effects of insulin treatment on glycemic control with regards to day-time hypoglycemia may vary." (PMID 27760129, 2016). "However, only 11 (26.8%) of 41 patients who experienced mild hypoglycemia and only 3 (15.0%) of 20 patients who experienced severe hypoglycemia had assistance from family members at insulin injections." (PMID 26102197, 2015). "The low affinity may permit dissociation of free insulin contributing to the late hypoglycemia, if the binding equilibrium is perturbed." (PMID 26241232, 2015). "Since they do not cause significant hypoglycemia (as opposed to insulin), thus can be safely administered at relatively high doses peripherally." (PMID 27152105, 2015). "In this hospital based practice, we could simply focus on reducing the basal infusion rate to prevent hypoglycemia and increasing bolus insulin dosage for the fixed carbohydrate amount in meals." (PMID 25785276, 2015). "In this study, adding sitagliptin effectively reduced HbA1c by 0.9% without an increased risk of hypoglycemia or weight gain in Japanese patients with T2DM whose glycemic control was suboptimal despite at least twice daily injections of insulin." (PMID 25816296, 2015). "Depending on glycemic control, the total daily dose may be reduced by 10–20% or more in case of frequent hypoglycemia or high total insulin dose during MDI, then using 30–50% of total daily dose as daily basal rate." (PMID 25802842, 2015). "The median dose of insulin in patients with unexpected hypoglycemia was 15 IU (IQR, 14–16) per day." (PMID 25961056, 2015). "In particular, the indices showed that vildagliptin reduced glycemia without increasing the risk for hypoglycemia, which is a clinical experience with vildagliptin added to insulin." (PMID 26587020, 2015). "Although not observed as often as that seen with insulin, SU carries a relatively greater risk of hypoglycemia." (PMID 26382923, 2015). "During hypoglycemia, her insulin level was detected to be very high (78.8 μIU/mL)." (PMID 26316438, 2015). "The failure to reach titration goals in the majority of both treatment groups, along with the lower doses of insulin, has the potential to mask any advantages of glargine treatment with regard to the avoidance of hypoglycemia and perceived benefits from a patient perspective." (PMID 26055391, 2015).
Hypoglycemia (continued). "In addition to increased peripheral glucose utilization, dysregulated insulin secretion induces profound hypoglycemia and neuroglycopenia by inhibiting glycogenolysis, gluconeogenesis and lipolysis." (PMID 26399329, 2015). "We therefore speculate that the danger of hypoglycemia is the reason for the unique ability of insulin, acting via a single receptor, to lower blood glucose." (PMID 25982967, 2015). "Conversely, activating heterozygous GCK mutations have been reported as cause of an opposite phenotype, characterized by inappropriate over secretion of insulin despite hypoglycemia, called hyperinsulinemic hypoglycemia (HH), with a growing number of mutations being reported ever since." (PMID 26587058, 2015). "Thus, the relative weight-adjusted dose of insulin required to achieve hypoglycaemia during the insulin tolerance test (ITT) is often higher, which is however reflected by the fasting glucose level." (PMID 26239687, 2015). "Most episodes of hypoglycemia occurred due to insulin overdose or irregular food intake and could be easily prevented by insulin dose adjustment or lifestyle modification." (PMID 25961056, 2015). "In insulin-treated patients with unexpected and refractory hypoglycemia even after insulin therapy was gradually reduced or even withdrawn, IAbs induced by exogenous insulin should be considered, and insulin withdrawal might be promptly needed." (PMID 25961056, 2015). "To explore the role of risk factors associated with T2DM in this context, we adjusted for duration of T2DM, history of insulin treatment, insulin secretagogues or other anti-diabetic medications, hypoglycemia episodes, fasting serum insulin and fasting glucose in model." (PMID 26098780, 2015). "In general the frequency of hypoglycemia is greatest with insulin and insulin secretagogues that are excreted primarily by the kidney and/or have active metabolites that may accumulate in patients with impaired renal function such as glibenclamide (glyburide)." (PMID 26239457, 2015). "This may in part be attributed to GABA-induced counter regulatory mechanisms, especially elevated glucagon, which prevent hypoglycemia in the face of increased insulin levels." (PMID 26617516, 2015). "Though the decision to adjust insulin doses at initiation is clearly influenced by specific patient characteristics such as level of glycemic control and current frequency of hypoglycemia, inherent antihyperglycemic features of SGLT2 therapy in patients with T1DM requires further analysis." (PMID 26544192, 2015). "Acute metabolic stress such as insulin-induced hypoglycemia triggers a counterregulatory response during which the release of catecholamines (epinephrine), the activation of tyrosine hydroxylase (TH) enzyme and subsequent compensatory catecholamine biosynthesis occur in the adrenal medulla." (PMID 25713330, 2015). "With incidences of approximately 2 per patient per week for mild (i.e. self-treated) hypoglycemia, and 0.1-1.5 per patient year for severe hypoglycemia (SH), hypoglycemia is both the main limitation in achieving glycemic targets and the main side effect of intensified insulin therapy in T1DM." (PMID 26292721, 2015). "The main question, however, is whether hypothermia following (insulin-induced) hypoglycemia is anapyrexic in nature." (PMID 30873441, 2015). "The questions asking knowledge about hypoglycemia revealed that SU or insulin users had significantly more knowledge of hypoglycemia than others (P < 0.001); however, 63% of patients using insulin, and 31% of patients using SU always carried glucose or a similar medication with them." (PMID 26566411, 2015). "There are various causes of hypoglycemia, such as oral hypoglycemic drugs or insulin overdose, poor oral intake in diabetic and nondiabetics, undiagnosed insulinoma, sepsis, renal or hepatic failure, or Addison’s disease." (PMID 30039063, 2015).
Hypoglycemia (continued). "Accordingly, because these drugs reduce both fasting and postprandial blood glucose levels with no risk of hypoglycemia, they clearly have higher efficacy than sulfonylurea agents, which are conventional insulin secretagogues." (PMID 25780477, 2015). "Several factors including blood pH, insulin and catecholamine levels, potassium intake, and renal function might influence the serum potassium levels in patients with severe hypoglycemia." (PMID 25192953, 2015). "Despite incremental improvements in care since the discovery of insulin therapy in 1922, current clinical outcomes remain suboptimal, with current intensive insulin therapies limited by hypoglycaemia and few patients able to achieve adequate long-term glycemic control to prevent end organ damage." (PMID 25881192, 2015). "Such agents are designed to mimic the natural physiologic effects of insulin within the human body without a defined peak in activity, thereby decreasing the risk of a hypoglycemia-related side effect." (PMID 26120575, 2015). "When these high serum potassium concentrations were treated with insulin, severe hypoglycemia may have resulted." (PMID 26100120, 2015). "Following the addition of an SGLT2 inhibitor to his regimen he was able to avoid severe hypoglycemia by reducing or even omitting his preprandial short-acting aspart insulin which was only administered if his preprandial glucose was over 200 mg/dL which usually only occurred once daily." (PMID 25785209, 2015). "Given its central role in the regulation of insulin release, it is understandable that inactivating or activating mutations in the GCK gene may cause either hyper or hypoglycemia, respectively." (PMID 26587058, 2015). "However, spontaneous hypoglycemia occurred recurrently even after discontinuation of insulin, and thus they were admitted to the hospital for further examination and management." (PMID 25961056, 2015). "Furthermore, the proportion of patients that experienced nocturnal hypoglycemia was much higher in the NPH insulin group (RR, 1.22; 95 % CI, 1.09–1.37; p < 0.001)." (PMID 26055391, 2015). "Metformin, thiazolidinediones, dipeptidyl peptidase-4 inhibitors, glucagon-like peptide 1 (GLP-1) mimetics and sodium glucose cotransporter-2 (SGLT2) inhibitors do not increase the risk of hypoglycemia when used without sulfonylureas or insulin." (PMID 26239457, 2015). "MET + SU + GLP-1-RA reduced the odds of hypoglycaemia compared to MET + SU + insulin." (PMID 26664803, 2015). "Unfortunately only 36.5% patients receiving insulin therapy, 25.2% using SU agents, and 21.7% of those not using insulin or SU agents had knowledge of the causes of hypoglycemia." (PMID 26566411, 2015). "Intranasal intake of insulin enhanced long-term declarative memory and positively affected mood in humans without causing systemic side effects like hypoglycaemia." (PMID 26136647, 2015). "Transplantation resulted in significantly reduced episodes of hypoglycaemia and improved awareness of hypoglycaemia, with a reduction in insulin requirements and an improved beta score of ≥3 at all assessment time points post-transplantation over the 1 year period." (PMID 25810037, 2015). "In addition, this Cmpd1-mediated synergistic effect on glucose lowering diminishes unexpectedly when glucose approaches hypoglycemia levels, even though Cmpd1 extended insulin’s duration of action significantly under the same conditions." (PMID 25799496, 2015). "At this early age where the treatment at home of the toddler totally depends on her family, it is therefore important to arm the parent or carer with the necessary information as concerns feeding, insulin treatment and most especially the recognition and the management of hypoglycemia." (PMID 26966489, 2015). "The dissociation constant of antibody-bound insulin in some cases has indicated that sufficient free insulin could be released to produce hypoglycemia." (PMID 26241232, 2015).
Hypoglycemia (continued). "Inhibition of NO synthase activity has also recently been reported to attenuate the increases in CBF during insulin-induced hypoglycemia in anesthetized, mechanically ventilated piglets, suggesting that NO plays a role in mediating the cerebrovascular response to hypoglycemia." (PMID 26528968, 2015). "The subjects may thus develop nocturnal hypoglycemia, as the effect of insulin given in the evening or before bedtime peaks during nighttime." (PMID 26625003, 2015). "Morning cortisol level was normal and the C-peptide level was low at 0.42 which suggested nonpancreatic insulin source as the cause of hypoglycemia." (PMID 26839722, 2015). "After having observed frequent hypoglycemic episodes, on average, one every three days, in our patients treated with s.c. insulin according to the basal-bolus correction scheme, as suggested in the literature, we drew up nurse-managed procedures aimed at preventing hypoglycemia." (PMID 25961051, 2015). "Among them, only two patients on SU or insulin therapy experienced severe hypoglycemia." (PMID 25699116, 2015). "An inpatient study randomizing weight-based basal and bolus insulin in patients with a GFR <45 mL/min/1.73 m2 to 0.5 units/kg body weight vs. 0.25 units/kg showed similar glycemic control but significantly less hypoglycemia in the group with the lower weight-based dose." (PMID 28702221, 2015). "In spite of never given insulin as the sole treatment of ketosis, because of the risk of hypoglycemia, Ins received cows showed better energy metabolism than controls." (PMID 26422371, 2015). "After the renal denervation, a hypoglycemia was induced and maintained via dosages of insulin." (PMID 26564063, 2015). "After binding to GLP-1 receptor, GLP-1 stimulates insulin secretion in a glucose dependent manner, which means there is no or little risk of hypoglycemia." (PMID 26351642, 2015). "As this factor has been associated with a lower quality of life, it appears that controlling hypoglycemia may be the most important consideration when the physician is selecting the type of insulin to prescribe." (PMID 26055391, 2015). "Alternatively, it may occur due to the effect of basal insulin peaking during nighttime thus inducing nocturnal hypoglycemia." (PMID 26625003, 2015). "With regard to monotherapy with OHAs, incidence of hypoglycemia was high in the patients using drugs to promote insulin secretion as 4% for SU agents and 3.8% for glinide agents, followed by 3.5% for pioglitazone, whereas ≤ 2% in patients using metformin, DPP-4 inhibitors, or α-GIs." (PMID 26566411, 2015). "Previous hypoglycemia (OR: 11.24; 6.71–18.85), duration of insulin treatment (days) (1.06; 1.05–1.07), history of transient ischemic attack (TIA)/stroke (1.91; 1.04–3.50), and former salicylate prescriptions (1.44; 1.06–1.98) also showed an increased odds of having hypoglycemia." (PMID 25698911, 2015). "However, transient hypoglycemia should be alerted due to the release of previously combined insulin from the IAb-insulin complex when the autoantibody was erased." (PMID 25961056, 2015). "Since SGLT-2 is expressed exclusively in kidney thus its inhibition act as a therapeutic target in T2DM without risk of hypoglycemia since it increases renal excretion of glucose without influencing insulin secretion (Edward and Robert, 2010)." (PMID 27152105, 2015). "Based on these characteristics of DPP-4 inhibitors, adding a DPP-4 inhibitor to insulin is expected to improve glycemic control without an increase in risk of hypoglycemia and weight gain." (PMID 25816296, 2015). "The study’s objective was to compare the effect of adjunctive metformin vs. placebo on glycemic control, body mass index (BMI), waist circumference (WC), total daily dose (TDD) of insulin, and hypoglycemia in overweight/obese youth with T1D receiving multiple daily injections of insulin." (PMID 26367281, 2015).
Hypoglycemia (continued). "Hypoglycemia is a common and serious medical emergency that arises as a complication in patients attempting to tightly regulate glucose levels with insulin and is the limiting factor in the development of strategies that aim to maintain normoglycemia in diabetics." (PMID 26553727, 2015). "Other detriments of basal insulin therapy include risks for hypoglycemia and weight gain." (PMID 26594250, 2015). "However, in the same studies, reductions in severe and nocturnal hypoglycemia were found, especially with short-acting insulin analogues as compared to regular insulin and detemir as compared to NPH." (PMID 25964802, 2015). "The incidence of hypoglycemia was highest in patients receiving insulin therapy (OR 11.4)." (PMID 26566411, 2015). "Hypoglycemia is a common side effect of insulin or sulfonylurea therapy and may occur during driving." (PMID 28702227, 2015). "Histopathological examination of pancreatic resections done to search for an insulinoma has shown, in several cases, beta cell hyperplasia or hypertrophy, strongly suggesting that insulin overshoot is one mechanism of the late (4–8 hours postprandial) hypoglycemia." (PMID 26241232, 2015). "The medium long-acting NPH (neutral protamine Hagedorn) given at bedtime has been a common first-hand choice, but a long-acting insulin analogue (insulin glargine (IG) or insulin detemir (ID)) is frequently used, particularly in patients experiencing nocturnal hypoglycaemia." (PMID 28702235, 2015). "To test this hypothesis, we compared the effect of single daily (RH) and twice-daily episodes of insulin-induced hypoglycemia (2RH) on adrenal epinephrine release and production in normal rats." (PMID 25713330, 2015). "However, intensification of insulin therapy can increase the incidence of hypoglycaemia; the most common and unpredictable side effect of insulin treatment." (PMID 25421366, 2015). "In such patients, insulin tolerance testing may not be test of choice, due to an anticipated attenuation in physiologic response to acute insulin-induced hypoglycemia." (PMID 26425596, 2014). "At the time of confirmed hypoglycemia, the serum level of insulin and C-peptide was low." (PMID 24891941, 2014). "Moreover, 67% of the subjects treated with increasing insulin doses experienced at least one episode of hypoglycaemia, while only 28% of the subjects with adding glimepiride experienced at least one episode of hypogycaemia." (PMID 24650537, 2014). "This syndrome began early in childhood, with growth retardation and recurrent episodes of profound asymptomatic hypoglycemia (blood glucose concentration as low as 1.6 mmol/l), with an incomplete suppression of insulin concentrations (2 to 4 mIU/l), appearing between the ages of 2 and 5 ys." (PMID 25248098, 2014). "Here, the low incidence of hypoglycemia suggests that the nurses were experts in insulin titration." (PMID 24598381, 2014). "Significant predictors of having a depressive mood included female gender, single marital status, current and past smoking status, lack of physical activity, higher BMI and total cholesterol level, increased number of comorbidities, presence of history of hypoglycemia, and insulin treatment." (PMID 25431771, 2014). "Therefore, reducing pre- and also post-exercise rapid-acting insulin dose is an effective strategy for preventing exercise-induced hypoglycaemia." (PMID 24858952, 2014). "Though basal insulin with metformin or sulfonylurea is an effective therapy, it cannot reduce postprandial glycemia without the risk of hypoglycemia." (PMID 24684803, 2014). "Insulin therapy is recognized to possess the most striking and definite effect on glucose lowering in diabetic patients with the inevitable adverse effects such as hypoglycemia and weight gain." (PMID 27419209, 2014). "The bound insulin may readily dissociate from the IABs, resulting in a rapid increase in free insulin levels and consequent hypoglycemia." (PMID 25289063, 2014).